TNF (tumor necrosis factor)
Diseases named in the same sentence as TNF in open-access papers (continued):
Sharing a sentence is not in itself a finding about the gene and the disease.
mycoplasma infection (10 papers, 2008 to 2025). "The compelling comparison with the mycoplasma microbiome signature to the altered group showed a log ratio of 0.17 with a p-value of 0.0334, revealing that mycoplasma infection is significantly more abundant in a high TNF mRNA expressing patient group." (PMID 37867861, 2023). "In this study, we report that persistent mycoplasma infection promotes the secretion of a significantly high level of TNF-α in PCa cells leading to activation of the NF-κB pathway and in vitro characteristics of PCa progression." (PMID 37867861, 2023). "TNF-α is involved in pathogenesis of mycoplasma infections and can also reflect immune response and protectioninduced by vaccines." (PMID 36014052, 2022). "It is been shown that Mycoplasma infection induces a secretion of IL-8 and TNF-α by human lung epithelial cells in vitro." (PMID 18513407, 2008). "When mycoplasma infection occurs, macrophages produce TNF-α to increase the inflammatory response." (PMID 30157804, 2018). "Specifically, measurements of other Th1 cytokines, such as TNF‐α, interleukin (IL)‐2, and IL‐12, and of T‐cell proliferation and cytotoxic activity may reveal further aspects of T‐cell exhaustion in bovine mycoplasmosis." (PMID 28544524, 2017). "Taken together, these data suggest a strong correlation between mycoplasma infection and high TNF-α expressing PCa in vivo and altered TNF-α expressing PCa attributes of aggressive tumor malignancy phenotypes." (PMID 37867861, 2023). "In TLR2 knockout (TLR2-/-) mice, the levels of TNF-α in bronchial alveolar lavage fluid (BALF) and peripheral blood after mycoplasma infection and the pathological changes in the lung tissue of mice were detected." (PMID 35372108, 2022). "Although there was the relatively low correlation between TNF mRNA expression and mycoplasma infection in TCGA data compared to TMA staining data, M. hyorhinis may have a considerable effect for TNF expression in PCa." (PMID 37867861, 2023).
Mycoplasma pneumonia (10 papers, 2018 to 2025). "Upregulation of miR-143-3p expression reduced TNFα, MyD88, p50, and alveolar epithelial cell apoptosis in mycoplasma pneumonia mice by inhibiting TLR4/MyD88/NF-κB axis." (PMID 35812870, 2022). "Increases the number of A549 cells; down-regulates IL-8 and TNF-α expression; and benefits Mycoplasma pneumoniae pneumonia through chemokine ligand 5–chemokine receptor 4 interaction." (PMID 35566359, 2022). "Moreover, ATF3 can inhibit the release of inflammatory factors TNF‐α, IL‐1β, IL‐6, and IL‐18 induced by Mycoplasma pneumonia." (PMID 37385291, 2025). "Our team's previous research verified that TNF-α was significantly high in RMPP children, which is a good predictor for refractory Mycoplasma pneumoniae pneumonia." (PMID 35770160, 2022). "One in vitro study of MGD on serum of children with Mycoplasma pneumonia also showed that MGD suppressed L-1β, IL-18, TNF-α, down-regulated NLRP3, pro-IL-1β, Caspase-1, pro-Caspase-1, and GSDMD-N in infected cultures and mitigated NLRP3 overexpression-induced pyroptosis." (PMID 36120338, 2022). "The cytokines tumor necrosis factor-alpha, interleukin-8, interleukin-6, and interleukin-1 beta were detected in the airway secretions of children infected with RSV and Mycoplasma pneumonia, which may act as a double whammy of respiratory pathogens and correlate with severe pathogenesis." (PMID 36422931, 2022).
obstructive jaundice (10 papers, 1994 to 2024). A finding indicating increased bilirubin levels in the blood and urine, due to intrahepatic or extrahepatic obstruction of the biliary system. "Clinical studies have shown that patients with obstructive jaundice are predisposed to systemic inflammatory reactions characterized by high levels of pro-inflammatory cytokines [e.g., IL6 and TNF (tumor necrosis factor, TNF-α)]." (PMID 38319509, 2024). "To further evaluate the excessive pulmonary inflammation induced by LPS in rats with obstructive jaundice, we observed changes in the expression of inflammatory cytokines TNF-α and IL-6 in lung tissue." (PMID 39744639, 2024). "At the same time serum levels of TNF-α and IL-1 β in rats with obstructive jaundice showed significant increases." (PMID 18045488, 2007). "The wound healing process and production oftumour necrosis factor alpha (TNF-α) by peritonealcells of 7-day and 14-day obstructive jaundice (OJ)and sham-operated rats were investigated." (PMID 10674746, 2000). "We have investigatedthe relationship of obstructive jaundice to the neutrophil oxidase response and the “priming” of theresponse by the cytokines TNFα, interleukin-1 (IL-1), IL-6, and IL-8." (PMID 8204547, 1994). "It reduced the expression of tumor necrosis factor-alpha (TNF-α), nuclear factor kappa B (NF-κB), transforming growth factor-beta (TGF-β), interleukin-6 (IL-6) mRNA in mouse serum, and restored liver cells in obstructive jaundice mice." (PMID 38998501, 2024). "Purpose. we aim to explore the protective effects of Salvia miltiorrhizae injection on multiple organs of obstructive jaundice (OJ) rats through observing the impact of this injection on the pathological alterations in these organs and the contents of endotoxin, PLA2, and TNF-α in the blood." (PMID 19672457, 2009).
papilloma (10 papers, 2016 to 2024). A benign epithelial neoplasm that projects above the surrounding epithelial surface and consists of villous or arborescent outgrowths of fibrovascular stroma. "Selective TNF-α deletion in CD19 + -Cre B cells significantly reduced papilloma development compared to B cells from WT mice (p < 0.002)." (PMID 31901949, 2020). "Reduced IKKα accelerates well-differentiated papilloma development and loss of two Ikka alleles promotes the transition from well-differentiated skin papilloma to poorly differentiated SCC associated with increased TNF expression." (PMID 36270982, 2022). "Additionally, selective elimination of TNF production by B-cells resulted in a decreased papilloma incidence, while B-cell transfer from DMBA/TPA-treated WT mice into TNF-deficient mice rescued tumor development, comparably to wild-type recipients." (PMID 33917839, 2021). "Similarly, compared to B cells with selective TNFα deletion, adoptive transfer of B cells from wild type mice into TNFα knockouts notably stimulates papilloma development in DMBA/TPA murine model of skin tumorigenesis, highlighting the tumor-promoting function of Breg, the known source of TNFα." (PMID 36249034, 2022). "Using pentoxifylline, which was shown to inhibit TNF and IL-1a gene expression, the growth of DMBA/TPA induced papillomas were inhibited." (PMID 27389279, 2016). "Immature LCs from the papillomas and foreskin expressed high levels of CCL20 mRNA that were close to GAPDH levels at baseline, with no significant change after removal from their microenvironments or following stimulation with either poly(I:C) or TNFα." (PMID 32210959, 2020). "Subsequent stimulation of papilloma iLCs with poly(I:C) or TNFα did not further increase their high level of CCL1 mRNA expression." (PMID 32210959, 2020). "In a DMBA/TPA murine model of skin carcinogenesis adoptive transfer of B cells from DMBA/TPA wild type (WT) mice into TNF-α knockout mice significantly increased papilloma development (p < 0.05), an effect not seen when B cells from the TNF-α knockout mice were transferred to RAG2−/− mice." (PMID 31901949, 2020). "Moreover, the average number of papillomata per mouse in Lgr5-Pten-/--TNF-/-mice was much lower compared to that in Lgr5-Pten-/- mice, and TNF-/- mice did not develop papilloma when receiving the same DMBA /TPA treatment." (PMID 31754399, 2019).
pharyngitis (10 papers, 2020 to 2025). Inflammation of the throat most often caused by viral and bacterial infections. "MAIT cells are highly activated to release IFNγ, IL-1β, IL-2 and TNF, which are involved in pharyngitis, invasive GAS disease and ARF." (PMID 40276383, 2025). "Protein expressions of MAPKs, NF-κB, COX-2 and 5-LOX in pharyngitis tissue were evaluated by western blot analysis and the levels of TNF-α, IL-6, prostaglandin (PG) E2, leukotrienes (LT)-B4 and LT-D4 in pharyngeal tissue were measured via ELISA assay." (PMID 32928206, 2020). "Nevertheless, these outcomes recommend that the inhibitory effects of YHQ on 5-LOX/LT-B4/LT-D4 and COX-2/PGE2 are consistent with its inhibitory effects on pro-inflammatory cytokines (IL-6 and TNF-α) in ammonia-induced pharyngitis." (PMID 32928206, 2020). "Moreover, Gancao Jiegeng Shegan Decoction can regulate the levels of cyclooxygenase-2 and PGE2; reduce the serum TNF-α, IL-1β, and IL-6 levels; reduce throat inflammation; and exert expectorant effects." (PMID 38464723, 2024). "CQQN can improve pharyngitis by regulating the TNF and IL-17 signaling pathways." (PMID 35528163, 2022). "Animal experiments showed that CQQN could significantly reduce the expression of TNF-α, IL-1β, IL-6, and IL-17 in the serum of rats with pharyngitis (P < 0.05)." (PMID 35528163, 2022). "Many traditional Chinese medicine formulations exert their therapeutic effects in treating pharyngitis by suppressing the release of inflammatory factors, including IL-6, IL-1β, PGE2, and TNF-α, etc." (PMID 39568590, 2024). "The inhibition of YHQ on TNF-α and IL-6 implied that alleviation of YHQ on pharyngitis may depend on down-regulation of inflammatory mediators." (PMID 32928206, 2020).
polyarticular JIA (10 papers, 2009 to 2025). "TNF inhibitors that are internationally approved for polyarticular JIA are adalimumab, etanercept, and golimumab in patients at least aged 2 years." (PMID 40089767, 2025). "The tumor necrosis factor inhibitors (TNFi) have shown tremendous benefit in children with polyarticular JIA and likely in enthesitis-related arthritis and psoriatic JIA as well." (PMID 24782683, 2014). "Blocking TNF-α by using subcutaneous etanercept has proven its efficacy and safety for the treatment of polyarticular JIA." (PMID 19200377, 2009). "For instance, S100A8/A9 and S100A12 can serve as diagnostic biomarkers and are associated with response to anti-tumor necrosis factor (TNF) treatment in systemic JIA patients.14-3-3η has been found to have the potential to serve as a new biomarker for polyarticular JIA." (PMID 40852723, 2025). "Over the following years other anti-TNF inhibitors, including adalimumab, infliximab, and golimumab, the IL-6 inhibitor tocilizumab, and costimulatory disruption abatacept were tested in RCTs that included patients with polyarticular JIA." (PMID 37475055, 2023). "In 1999, etanercept (ETN) became the first anti-tumor necrosis factor (anti-TNF) therapy approved by the Food and Drug Administration (FDA) for polyarticular JIA, and has since been shown to be effective in multiple categories of JIA." (PMID 34419107, 2021).
radiculopathy (10 papers, 2011 to 2025). Disease involving a spinal nerve root (see spinal nerve roots) which may result from compression related to intervertebral disk displacement; spinal cord injuries; spinal diseases; and other conditions. "Blocking TNF activity through either TNF sequestration or competitive inhibition of membrane-associated TNF receptors may potentially modify disease processes associated with radiculopathy." (PMID 21871102, 2011). "Immense levels of circulating cytokines, along with TNF-α, have been observed in patients suffering from radiculopathy after disk herniation." (PMID 41303319, 2025). "High levels of circulating cytokines including TNF-α are seen in patients suffering radiculopathy following disc herniation." (PMID 30584238, 2018). "IL-1β, TNF-α and other pain-mediating chemicals released from the NP can irritate dorsal root ganglions, contributing to functional and structural nerve damage, radiculopathy and muscle weakness in vivo." (PMID 27689996, 2016). "Significantly increased levels of TNF-α occur in herniated and degenerate IVD tissue, and are associated with radiculopathy following herniation." (PMID 23565184, 2013). "Randomized human clinical trials and prospective studies also tested the hypothesis that TNF-α inhibition improved radiculopathy by measuring pain on a visual analog scale." (PMID 37206531, 2023). "TNF-α is a cytokine with pro-inflammatory properties that increases the expression of endothelial selectin, leading to acute-phase protein production within the liver that can be seen in pathology such as radiculopathy." (PMID 37206531, 2023). "In conclusion, elevated systemic TNF-α increases the susceptibility of mice to spontaneous disc herniation and possibly radiculopathy, without adversely affecting intact intervertebral disc health." (PMID 30584238, 2018). "While it is known that Etanercept blocks the activity of TNF-α, the exact role of TNF-α in radiculopathy pain is still unclear." (PMID 37206531, 2023). "Tumor necrosis factor-α (TNFα) has received significant attention as a mediator of lumbar radiculopathy, with interest in TNF antagonism to treat radiculopathy." (PMID 21871102, 2011). "Presently, the routine use of TNF or NGF inhibitors is not supported in radiculopathy or chronic LBP." (PMID 41304859, 2025). "In the same radiculopathy model used in this study, mRNAs for pro-inflammatory cytokines are upregulated in the spinal cord and DRG as early as 1 hour after injury and antagonizing TNF-α and IL-1 after injury attenuates allodynia." (PMID 24278231, 2013).
retinal vasculitis (10 papers, 2012 to 2024). Inflammation of the retinal vasculature with various causes including infectious disease; lupus erythematosus, systemic; multiple sclerosis; behcet syndrome; and chorioretinitis. "However, retinal vasculitis was negatively associated with complete response to anti-TNF-α treatment in multivariate analysis." (PMID 33171664, 2020). "Overall, AAV-mediated expression of TNF-α induced inflammation in the mouse eye, as seen by cellular infiltrates in the vitreous and retinal vasculitis." (PMID 34520511, 2021). "The expression of TNF-α induced strong inflammation in the mouse retinae, including immune cell infiltration into the vitreous, as well as retinal vasculitis and fibrosis." (PMID 34520511, 2021). "Additionally, the fundus of TNF-α expressing mice showed white cellular infiltrates around the optic nerve and the vasculature, indicating retinal vasculitis (white arrows)." (PMID 34520511, 2021). "Systemic and retinal vasculitis induced by anti-TNF treatment, with or without accompanying retinal vein occlusion, has been reported in approximately 4% in some series." (PMID 38842591, 2024).
rhabdomyolysis (10 papers, 2005 to 2025). Necrosis or disintegration of skeletal muscle often followed by myoglobinuria. "The serum creatinine, TNF‐α, and NF‐κB expression increased and antioxidant capacity decreased in the kidney injury caused by rhabdomyolysis and then the pathological evaluations approved it." (PMID 39803217, 2025). "In another case report, a patient who developed coxsackie associated rhabdomyolysis was found to have an elevated level of serum tumor necrosis factor (TNF), which has been shown to induce skeletal muscle breakdown in an animal model." (PMID 37344851, 2023). "In summary, the results of the present study demonstrated that kidney tissue damage and functional impairment associated with rhabdomyolysis, as well as the inflammatory response caused by increased NF‐κB and the proinflammatory cytokine TNF‐α, may be alleviated by C. botrys." (PMID 39803217, 2025). "In this context, a kidney biopsy of a patient with rhabdomyolysis-AKI had increased TNF-α and lipid peroxidation and was accompanied by infiltration of myeloid cells and lymphocytes." (PMID 36160140, 2022). "NLRP3 depletion decreased the mRNA expression of inflammatory cytokines, including TNF-α, IL-1β, and IL-6, induced by rhabdomyolysis." (PMID 33202867, 2020). "The involvement of TNF-α in injuries following rhabdomyolysis is significant." (PMID 38629092, 2024). "The current study aimed to investigate the effects of C. botrys plant extract on NF‐κB expression, TNF‐α serum levels, and TAC in a model of AKI induced by rhabdomyolysis." (PMID 39803217, 2025). "TNFα, IL-1β and IL-6 levels were significantly increased in kidney tissue from CRAMP-/- mice subjected to the rhabdomyolysis model compared with the wild-type counterparts (p < 0.01, p = 0.02 and p = 0.03, respectively)." (PMID 33456345, 2021). "β-defensin 3, thus, together with NGAL, TNFα, IL-1β and IL-6 are the proinflammatory mediators directly responsible for the worst outcome of CRAMP-/- mice subjected to the rhabdomyolysis model." (PMID 33456345, 2021).